TNF (tumor necrosis factor)
Diseases named in the same sentence as TNF in open-access papers (continued):
Sharing a sentence is not in itself a finding about the gene and the disease.
Arthritis (continued). "Depending on the TNF-α blockade strategy, treating arthritis with a TNF-α inhibitor could result in a different profile of infection suceptibility." (PMID 29184553, 2017). "Additionally, anti-IL-6/anti-IL-21 treatment of CIA mice during the arthritis induction phase reduced disease development more potent than IL-6 or IL-21 inhibition alone, as effective as anti-TNF treatment." (PMID 28158305, 2017). "The joint damage with our mono-arthritis model is reminiscent of the changes that occur with RA (Kannan, Ortmann & Kimpel, 2005) with increases in systemic inflammatory mediator Tumor Necrosis Factor alpha (TNF-α)." (PMID 27833798, 2016). "As a cytokine that mediates joint inflammation in arthritis, tumor necrosis factor α (TNF-α) was also found able to decrease SIRT1 activity and induce its cathepsin B-mediated cleavage and result in cartilage-specific gene expression inhibition in TNF-α-treated cells." (PMID 27863529, 2016). "However, clinical signs of arthritis, such as paw swelling and reduction of grip strength, were almost completely reversed with use of a TNF blocker." (PMID 27638666, 2016). "In this study, we first confirmed the therapeutic effects of MSCs on CIA mice, using generally applied quantification methods, including the paw thickness, clinical arthritis score, histological arthritis score, and modulation of proinflammatory cytokines, like IL-1β, IL-6, TNF-α, IL-10 and TGFβ1." (PMID 27354158, 2016). "Apoptotic cell injection or anti-TNF blockade demonstrated a similar reduction in arthritis, but, when co-administered, apoptotic cells and anti-TNF antibody demonstrated a stronger reduction in the severity of arthritis." (PMID 27516061, 2016). "TNF is a major cytokine in the context of experimental and human arthritis." (PMID 26742100, 2016). "To assess the effects of ferulic acid therapy on TNF-Tg mice with arthritis, we treated a cohort of TNF-Tg mice for 12 weeks and examined changes in lymphatic flow, lymphatic contraction frequency, LSMC gene expression, synovitis, and focal erosions by NIR-ICG imaging, qPCR, and histology." (PMID 26970913, 2016). "Besides the already mentioned effect of blocking TNF, glucocorticoids, which are widely used in RA, also suppress progression of arthritis." (PMID 27313578, 2016). "Mice deficient in PAD4 have reduced TNF-α-induced and glucose-6-phosphate isomerase-induced arthritis, but it is not known if PAD4 impacts lung citrullination or inflammation." (PMID 27450561, 2016). "Moreover, administration of IL-33 in human TNF-α transgenic mice, with spontaneous development of arthritis, inhibited bone destruction and reduced the number of osteoclasts." (PMID 27317338, 2016). "We suggest that the role of TNF in arthritis-associated metabolic changes is not due to local neutrophils, which are the major cells present in this model, but rather due to cytokines." (PMID 26742100, 2016). "When arthritis is uncontrolled or when DMARDs result in toxic effects, biological agents, for example, tumor necrosis factor (TNF) inhibitors and agents targeting the interleukin- (IL-) 1 and IL6 pathways, T-cell costimulatory pathways, and B cells will be used." (PMID 27642302, 2016). "Previous reports demonstrated the clinical benefits of antibiotic and TNF-α inhibitor combination therapies relating to both arthritis severity and bone destruction in addition to reductions in the mortality rate by a combination therapy in experimental S. aureus–induced septic arthritis." (PMID 27932936, 2016). "To explore further the role of GM-CSF as a pro-inflammatory cytokine, we examined the effect of anti-GM-CSFRα neutralization on myeloid cell populations in antigen-driven arthritis and inflammation models and also compared its effect with that of anti-TNF and anti-IL-6." (PMID 27908288, 2016).
Arthritis (continued). "Another study highlighting the importance of TNF-α in RA vis-á-vis FoxP3+ Tregs reported that overexpression of TNF-α in human TNF-α transgenic mice led to the development of arthritis, with an increased number of Tregs expressing the TNF receptor II (TNFRII)." (PMID 30873466, 2016). "In collagen-induced arthritis (CIA), a mouse model of RA, amelioration of arthritis during anti-TNF treatment has intriguingly been shown to increase the numbers of Th17 cells in draining lymph nodes, while reducing the numbers of these cells in the inflamed paws." (PMID 28010726, 2016). "Thus, proinflammatory cytokines (particularly IL-1β, IL-6, and TNF-α) play an important role in arthritis onset, while inhibitors of these cytokines are effective in controlling chronic inflammation." (PMID 27382402, 2016). "Our study supports the use of IGRA instead of TST to result in fewer arthritis patients with an indication for anti-TNF therapy and treated for LTBI without increasing their risk of developing active TB." (PMID 25746854, 2015). "Furthermore, Padi4 KO TNF alpha transgenic (Tg) mice had milder arthritis and less activated CD4+ T cells and some ACPAs than WT–TNF alpha Tg mice." (PMID 26293116, 2015). "Notably, PGRN showed therapeutic effects in various TNF-mediated inflammatory arthritis models, including collagen-induced arthritis and spontaneous arthritis in the TNF-transgenic model." (PMID 26408020, 2015). "Accordingly, we recently identified synovial markers of response to methotrexate, TNF blockade, tocilizumab or rituximab therapy in patients with established RA, a demonstration that a “molecular” diagnosis and characterization of arthritis can lead to specific and clinically relevant decisions." (PMID 25927832, 2015). "NF-κB is a transcription factor that acts as a significant part on the onset of inflammation by modulating the expression of pro-inflammatory cytokine (TNF-α, IL-1β, IL-6 and IL-17) genes involved in immune responses, which are all closely connected with the pathogenesis of arthritis." (PMID 26709520, 2015). "Serum TNF-α was also reported to be increased after the onset of arthritis in AIA rats." (PMID 26546348, 2015). "Here, we demonstrated that a single treatment with FBP markedly attenuated arthritis, assessed by reduction of articular hyperalgesia, joint swelling, neutrophil infiltration and production of inflammatory cytokines, TNF and IL-6, while enhancing IL-10 production in two mouse models of arthritis." (PMID 26478088, 2015). "Previous reports showed that anti-TNF prevents the development of very early acute G6PI arthritis." (PMID 26653844, 2015). "However, the role for this cytokine in arthritis is more anti-inflammatory than anabolic because it increases the synthesis of IL-1ra and downregulates TNF-α." (PMID 26090267, 2015). "Thus, in addition to the well-known catabolic effects of TNFα on articular cartilage and bone, TNFα signalling would decrease the reparative responses of endogenous joint MSCs, thereby limiting cartilage/bone regeneration during arthritis." (PMID 25929877, 2015). "Therapeutic blockade of TNF could yield rapid decrease of plasma IL-6 level, and our previous study based on rat model of arthritis has revealed that HMLE strongly inhibited the excessive production of both TNF and IL-6." (PMID 25602164, 2015). "Indeed, recombinant human PGRN inhibits TNF-activated signaling and protected against inflammation in rodent models of arthritis." (PMID 26485648, 2015). "Thus, dual JAK + SYK inhibition also presents greater efficacy than anti-TNF treatment in this experimental model of severe arthritis." (PMID 26653844, 2015). "In the present study, we re-evaluated the usefulness of the QFT assay for diagnosis of LTBI in arthritis patients who received anti-TNF treatment in Korea, where the incidence of TB is intermediate (70–90/100,000 per year) and BCG vaccination is mandatory at birth." (PMID 25746854, 2015).
Arthritis (continued). "Neutrophil influx peaked at 16 hours and being consistent with the elevation of IL-1β, IL-8, and TNF-α release, which could be detected subsequently by 24 h after the induction of arthritis." (PMID 26221174, 2015). "(ii) Our mouse model of arthritis is mainly driven by TNF, an extremely rigorous and strong model, which might cover potential implications of other cytokines on the development of experimental arthritis." (PMID 25111378, 2014). "Likewise, recombinant Hsp72 (induced Hsp70) has been reported to lessen the severity of collagen-induced arthritis in mice, by lowering serum TNF-α and IL-6 concentration." (PMID 25053922, 2014). "Therefore, we sought to investigate the physiological relevance of these findings in a TNF-α driven animal model of arthritis, the hTNFtg mouse." (PMID 25111378, 2014). "The data are entirely consistent with the view that arthritis in this model is driven by human TNFα although murine factors upstream or downstream of human TNFα, or synergising with human TNFα, could also be important." (PMID 25344414, 2014). "Furthermore, chronic overexpression of TNF using a human TNF-transgenic mouse model of TNF-induced arthritis has been shown to be best reduced with a treatment of anti-TNF-antibody (infliximab) and recombinant human IL-1Ra (anakinra)." (PMID 24964765, 2014). "More recently, evidence has also been obtained demonstrating that the anti-inflammatory effect of Ebosin on rat collagen-induced arthritis is through suppressing production of interleukin-1β, interleukin-6 and tumor necrosis factor α at both transcriptional and posttranslational levels." (PMID 25048214, 2014). "Furthermore etanercept treatment protected against histological changes in the joints demonstrating the utility of the model for assessing anti TNFα effects in an arthritis setting." (PMID 25344414, 2014). "In the present study, based on the results, we also concluded that GTW nanoparticles significantly decreased adjuvant-induced arthritis, which may be due to the protection provided against interleukin and TNF induced cartilage destruction." (PMID 24549173, 2014). "IL-17 may also contribute directly to joint damage, because it was shown to act synergistically with TNFα and/or IL-1β to induce cartilage destruction in vitro and in experimental arthritis in vivo." (PMID 25436214, 2014). "In the current set of experiments we compared the standard CAIA model in wild type C57Bl/6 mice with CAIA induced in Tg1278TNFko mice with a view to developing an arthritis model that is dependent upon human TNF for the evaluation of novel therapeutic entities." (PMID 25344414, 2014). "Our results indicate that the blockade of IL-36 signaling in the TNF-mouse model has no key impact on the pathogenic course of TNF-induced arthritis and therefore does not protect from TNF-induced inflammation and bone loss." (PMID 25111378, 2014). "However, subsequent work in the human TNFα Tg197 transgenic mouse model of arthritis supported the therapeutic potential of anti-human TNFα in RA that was later confirmed by a small trial in RA." (PMID 25344414, 2014). "Overexpression of MARCH8 in DCs of a CII-induced arthritis mouse model leads to reduced arthritis as well as TNFα and IL6 expression in synovial tissues, indicating that expression of MARCH8 alters the local inflammatory immune response but not the systemic immune response." (PMID 27419207, 2014). "Since Joyce-Shaikh observed that TNF-α could promote MDL-1 expression in murine arthritis, we examined the role of TNF-α or IL-1β in the regulation of MDL-1 expression." (PMID 24465901, 2014). "When examined comparatively with its closely related TNF∆ARE/+ strain that systemically overproduces TNFα and develops chronic ileitis and arthritis, the TNFi∆ARE/i∆ARE strain offers a unique opportunity to study common and diverse pathways in joint and intestinal pathologies." (PMID 23977323, 2013).
Arthritis (continued). "As the progression of arthritis is usually accompanied by body wasting, swelling of joints, and movement impairment, we analyzed the alteration of these parameters in doxycycline-inducible human TNFα–transgenic mice during doxycycline application." (PMID 23740547, 2013). "Whereas, in acute inflammation, TNF-α protects against bacterial endotoxin, viruses, and parasites, provides increased nutrients for immune cells, and favors a proper host response, in chronic inflammation, TNF-α activates pathways responsible for numerous pathological conditions, such as arthritis." (PMID 24307884, 2013). "Indeed, in mice transgenic for human TNF-α, which develop spontaneous arthritis, both pools of Teffs and Tregs decrease during the disease course and increase during anti-TNF-α treatment." (PMID 23801992, 2013). "TNF-α is a known regulator of various inflammatory diseases including arthritis, psoriasis, inflammatory bowel disease, and is also involved in various pulmonary inflammatory diseases including bronchitis, chronic obstructive pulmonary disease (COPD), asthma and acute lung injury (ALI)." (PMID 23468959, 2013). "With regard to the involvement of TNF-α in osteoclastogenesis in arthritis, M-CSF blocking may be effective." (PMID 23762085, 2013). "In addition, blocking S100A9 resulted in diminished TNFα and IL-6 expression in a collagen-induced arthritis model." (PMID 23977231, 2013). "Fullerenes inhibited the edema, inflammation, cartilage/bone erosion, and TNF-α levels associated with arthritis in K/BxN serum transfer arthritis but not in collagen-induced arthritis." (PMID 24300561, 2013). "Interestingly, EGR1 is directly involved in TNF-α mediated upregulation of prostaglandin E2 leading to inflammation and arthritis." (PMID 23140489, 2012). "We speculate that apoptotic cells induced by the immunotoxin may be removed during the 14 days that had passed since the last injection Thus, intra-articular injection of immunotoxin may be useful for treating arthritis refractory to systemic anti-TNF therapy." (PMID 22551402, 2012). "This beneficial antigouty arthritis effect may be mediated, at least in part, by inhibiting TNF-α and IL-1β mRNA expression and protein levels in the synovial tissues." (PMID 23304232, 2012). "During this acute phase of the SCW arthritis model, joint swelling is TNF-α dependent." (PMID 22719976, 2012). "In addition, the efficacy of blocking TNFα suggests that DTH arthritis indeed shares immunological pathways with human RA." (PMID 22676339, 2012). "The importance of TNF-alpha in arthritis is well documented." (PMID 22505941, 2012). "We also performed an analysis of the production of inflammatory mediators in the mBSA-challenged and PBS-challenged hind paws on days 1 and 3 after DTH-arthritis induction on mice given prophylactic treatment with anti-TNFα mAb or the corresponding isotype control antibody." (PMID 22676339, 2012). "It is well known that TNF-alpha is highly involved in arthritis, notably in RA." (PMID 22505941, 2012). "T-5224 inhibited the expression of TNF-α and other cytokines in a mouse arthritis model, suggesting it may also inhibit LPS-induced TNF-α production." (PMID 23173923, 2012). "TNF-α is considered an important cytokine in the development of arthritis." (PMID 22470519, 2012). "Moreover, blocking c-Fms inhibits macrophage infiltration, TNFα production by macrophages, and OC formation and activation in several mouse arthritis models, and reduces TNFα-induced inflammatory arthritis, suggesting a therapeutic benefit in RA treatment." (PMID 22264405, 2012). "In this model, the deficiency of TNF, but not IL-6, suppressed the development of arthritis and skin inflammation." (PMID 23133751, 2012). "Inflammation derived from the direct activation of innate immunity may result in the production of TNF and the development of arthritis." (PMID 23133751, 2012). "The IL-1β and TNF-α were studied by ELISA in the ankle steeps of arthritis model." (PMID 21569552, 2011).
Arthritis (continued). "Also in agreement with our findings, met-RANTES treatment also reduced TNF-α and IL-1β levels in a rat arthritis model." (PMID 21799885, 2011). "Combination of RB200 with the TNFα blocker etanercept resulted in complete abrogation of arthritis, suggesting that HER-targeted therapies developed for the treatment of cancer may also be effective in RA." (PMID 21982514, 2011). "Addition of exogenous TNF-α or IL-1 into experimental models of arthritis induces synovitis." (PMID 22085488, 2011). "In the present review we summarize the clinical picture and pathophysiologic processes of bone and cartilage damage in RA, PsA, and AS, we describe the key insights obtained from the introduction of TNF blockade, and we discuss the future challenges and frontiers of structural damage in arthritis." (PMID 21624183, 2011). "TTP−/− mice developed severe inflammatory symptoms, including cachexia, spontaneous arthritis, dermatitis, and neutrophilia, mainly because of the overproduction of TNFα resulting from the increased stability of the TNF mRNA and subsequent higher rates of secretion of the cytokine." (PMID 21776382, 2011). "A similar “contralateral effect” (i.e. distal therapeutic effect) has been observed following intra-articular gene transfer of immunosuppressive cytokines, inhibitors of IL-1β and TNF-α, or NF-κB decoy oligonucleotides in rabbit or mouse models of arthritis and DTH." (PMID 21829629, 2011). "Exogenous GM-CSF and TNFα have both been shown to induce arthritis in mice." (PMID 21073728, 2010). "Although some children with IBD develop arthritis and are managed or co-managed by pediatric rheumatologists, it is more likely that pediatric rheumatologists will use methotrexate in combination with an anti-TNF mAb." (PMID 20712883, 2010). "Furthermore, Schubert and colleagues reported the protective effect of TNF antagonist in GPI-induced arthritis and arthritis was clearly B cell-dependent." (PMID 19660107, 2009). "The ability of some TNF-null mice to develop arthritis after serum transfer suggests that other mediators are required for RA disease progression, and that these mediators may act in association with TNF." (PMID 23283207, 2009). "It has been demonstrated that NO is involved in the pathogenesis of arthritis; enhanced TRAP activity of osteoclasts increases bone resorption and contributes to bone loss; and IL-1/TNF-α stimulate chondrocytes to increase production of MMPs and other degradative products." (PMID 19712471, 2009). "This arthritis can be controlled by TNFα antagonists, suggesting similar etiology to RA." (PMID 19660107, 2009). "TNF-α has been shown to be a first line initiator of inflammatory responses in joints since synovial lining cells express TNF-α prior to the appearance of other cytokines in a collagen induced arthritis model." (PMID 19695100, 2009). "The objective of this study was to understand the inhibitory mechanism of phospholipase inhibitor from python (PIP)-18 peptide in cultured synovial fibroblasts (SF), and to evaluate its therapeutic potential in a human tumor necrosis factor (hTNF)-driven transgenic mouse (Tg197) model of arthritis." (PMID 19765281, 2009). "In this study, we explored TNFα-related mechanisms of arthritis." (PMID 19660107, 2009). "Our results highlight a paradoxical arthritis-regulatory function of exogenous TNFα." (PMID 18380898, 2008). "This action of B8 may be useful in inflammatory diseases (arthritis, Crohn's disease and asthma where anti-TNFα therapy is, or has potential, to be of therapeutic benefit." (PMID 18671842, 2008). "With regard to cytokine dependency, anti-TNF-α mAb does not prevent the development of arthritis in K/B × N mice, and IL-6 deficiency has no influence on the development of arthritis by K/B × N serum transfer." (PMID 18534002, 2008).